CP (ceruloplasmin)
Diseases named in the same sentence as CP in open-access papers (continued):
Sharing a sentence is not in itself a finding about the gene and the disease.
Anxiety (14 papers, 2007 to 2025). Intense feelings of nervousness, tension, or panic often arise in response to interpersonal stresses. "In CP deficient mice, increased anxiety is associated with elevated levels of plasma corticosterone and decreased levels of serotonin and NA, as well as brain-derived neurotrophic factor (BDNF) and its receptor." (PMID 38001850, 2023). "This indicates that 10 mg/kg and 5 mg/kg ketamine treatment in female mice significantly decrease anxiety-like behavior in the open-field test, which is dependent on CP-AMPARs." (PMID 37358072, 2023). "Both measures of anxiety-like behavior revealed increased anxiety in all transgenic models (CP-Tg, APdE9, and APdE9/CP-Tg) measured by time spent in the lit compartment and open arms." (PMID 35197825, 2022). "CP-Tg mice exhibited significant anxiety-like behavior measured by greater times spent resting and in the margin with less time spent moving (p < 0.05)." (PMID 35197825, 2022). "APdE9/CP-Tg mice, along with age-matched controls, were subjected to behavioral tests to assess possible changes in cognitive and anxiety-like behaviors." (PMID 35197825, 2022). "On the other hand, for the behavioral alterations related to anxiety, the recovering effects of VD exceeded those of the CB agonist CP." (PMID 23394117, 2013). "AEA and the strong selective CB agonists ARA and CP partially attenuated the single NC-induced anxiety-related behavioral alterations in the elevated plus-maze test." (PMID 17877812, 2007). "This suggests that CP could be involved in reducing anxiety in stressful situations, and indeed in dairy cattle, CP has been shown to increase in relation to stress, e.g. around calving." (PMID 33917627, 2021). "Therefore, our findings indicated the involvement of hippocampal PV+ interneuron reduction in CP/CPPS link with anxiety-like behavior." (PMID 33815658, 2021). "The CP knockout mice showed elevated anxiety levels compared with normal mice." (PMID 33917627, 2021). "We also demonstrated that there was a strong correlation between increased anxiety-like behavior and number of hippocampal PV+ interneurons in CA2/3 and DG regions in CP/CPPS rats." (PMID 33815658, 2021). "Although single NC-induced anxiety-related behavioral symptoms were partially antagonized by selective CB agonists such as ARA and CP, repeated NC, like chronic stress, seemed to cause an enhanced stress-related response which was not antagonized by those CB agonists." (PMID 17877812, 2007). "APdE9 and APdE9/CP-Tg mice exhibited the same level of anxiety as the CP-Tg mice in the light-dark and elevated-plus maze behavioral tests suggesting PGI2 does not increase the anxiety effect observed in the AD model." (PMID 35197825, 2022).
depression (14 papers, 2014 to 2024). "Depression has been associated with disturbances in acute phase proteins (APP): ceruloplasmin, inter-alpha-trypsin inhibitor heavy chain H4 and complement component—1qC." (PMID 33255237, 2020). "Second, the CP-AMPAR-induced loss of dopamine neurons in the midbrain causes PD-related depression." (PMID 34483848, 2021). "Three to four days post-challenge with CP (ACP and GCP), the chicks showed decreased activity, depression, reluctance to move, loss of appetite, diarrhea, and ruffled feathers." (PMID 36985195, 2023). "This demonstrates that 10 mg/kg ketamine treatment in male mice significantly reduces depression-like behavior, which is mediated by CP-AMPARs." (PMID 37358072, 2023). "In support of this idea, dialyzing 20 mM BAPTA into α On RGCs with high CP-AMPAR expression (RI < 0.4) prevented delayed synaptic depression." (PMID 32792936, 2020). "An observational study found that a significantly greater CP volume in patients with depression was positively correlated with [11C]PK11195 PET (neuro-inflammatory markers) binding in the anterior cingulate, prefrontal, and insular cortices, but not with the peripheral inflammatory markers." (PMID 38961406, 2024). "Although the role of ceruloplasmin in depression remains uncertain, elevated serum levels of ceruloplasmin may indicate the potential significance of copper ions in mood disorders." (PMID 37894749, 2023). "Our results provide an example in which group 1 mGluR-mediated synaptic depression does not require or promote CP-AMPAR removal." (PMID 25152720, 2014). "Moreover, NMDAR and CP-AMPAR may serve as a depression-related modulator and be regarded as a promising therapeutic target for treatment of psychopathology such as depression." (PMID 33087756, 2020). "Moreover, some types of mGluR-mediated synaptic depression require the phosphorylation/dephosphorylation of the AMPAR subunit GluA2, which CP-AMPARs generally do not contain." (PMID 25152720, 2014).
glioma (14 papers, 2016 to 2025). A benign or malignant brain and spinal cord tumor that arises from glial cells (astrocytes, oligodendrocytes, ependymal cells). "A higher CP expression was significantly correlated with the glioma grade, age, chemotherapy status, IDH mutations, PRS type, and 1p19q co-deletion status in patients with glioma." (PMID 37637428, 2023). "In conclusion, these findings suggest that CP could be regarded as a novel immune-linked therapeutic target for glioma." (PMID 37637428, 2023). "The prognosis of the patients suffering from glioma was inversely linked to the high CP expression." (PMID 37637428, 2023). "Specific factors within the glioma microenvironment, notably tumor necrosis factor-α, and ceruloplasmin, actively attract and stimulate neutrophils to migrate toward and infiltrate glioma tissues." (PMID 39911305, 2025). "In the TCGA and CGGA databases, COX regression analysis revealed that CP was an independent factor that affected the prognosis of the patients suffering from glioma (p < 0.001)." (PMID 37637428, 2023). "According to these results, patients with glioma have better prognoses and levels of tumor immune cell infiltration when their CP expression is low." (PMID 37637428, 2023). "CP expression was seen to increase significantly with an increasing glioma grade in the TCGA, CGGA, Gravendeel, and Rembrandt databases." (PMID 37637428, 2023). "Free CP showed moderate toxicity against the glioma cell line at doses from 0.2 to 2.0 μg/mL, compared to the control." (PMID 36839993, 2023). "The copaiba CP in PEGylated liposomes showed antiproliferative action on glioma cells 1.06-fold more than when incorporated into conventional liposomes and 1.5 times more in the free-form for 30 μg/mL." (PMID 36839993, 2023). "Consistently, the CP expression was seen to be significantly differences (p < 0.001) in the glioma grade, gender and age, validated in the TCGA cohort." (PMID 37637428, 2023). "The cellular cytotoxicity studies of crude extract 19 and partitions (HDP (hydroalcoholic), HP (hexanic), CP (chloroform), and AEP (ethyl acetate) revealed that CP presented greater cytotoxic potential when compared to the crude extracts and the other partitions in glioma cells." (PMID 36771057, 2023). "The results revealed a significant increase in CP expression with relatively advanced glioma grade." (PMID 37637428, 2023). "Finally, in order to identify the cell viability kinetics, glioma cells were exposed to M. chamissois crude extract and its partitions HP and CP at 6, 12, 24, and 48 h." (PMID 36771057, 2023). "In addition, the clinical prognostic relevance of the CP in the patients suffering from glioma was explored." (PMID 37637428, 2023). "Studies using a variety of databases, including Chinese Glioma Genome Atlas (CGGA), The Cancer Genome Atlas (TCGA), and Gliovis, showed that the mRNA and protein expression levels of CP in patients suffering from glioma increased significantly with an increasing glioma grade." (PMID 37637428, 2023). "Finally, recently our group harnessed the knowledge of this bioprospect study to assess the antitumor potential and biological characterization of CP on glioma cell lines." (PMID 36771057, 2023). "CP might represent a new biomarker of prognosis and classification-based treatment in patients with gliomas." (PMID 37637428, 2023). "At present, the existing literature studies have reported that in the iron-deficient and iron-saturated cells, CP, regardless of concentration, promotes the uptake of transferrin-bound iron and ferric citrate by glioma cells." (PMID 37637428, 2023). "COX regression analysis in the TCGA and CGGA databases suggested that CP could serve as an independent prognostic factor that affected the prognosis of the patients suffering from glioma (p < 0.001)." (PMID 37637428, 2023).
glioma (continued). "CP was confirmed to be an independent prognostic factor for predicting the prognosis of glioma patients through bioinformatics analyses of the glioma databases, and its specific mechanism may be related to tumor immunity." (PMID 37637428, 2023). "As a result, CP could be used as a probable therapeutic target for gliomas and potentially anticipate the effectiveness of immunotherapy." (PMID 37637428, 2023). "Gliomas (oligodendrogial or astrocytic primary brain tumours) strongly express CP‐AMPARs." (PMID 33533533, 2021). "Therefore, CP could be regarded as an independent prognostic biomarker for glioma and could enable the development of the targeted precision oncology." (PMID 37637428, 2023). "In addition, the findings in this study revealed the correlation between the high CP expression in gliomas and increased infiltration of macrophages, B cells, neutrophils, dendritic cells, CD4+ T cells, and CD8+ T cells, with the help of the CiberSort and ESTIMATE algorithms and Timer portal." (PMID 37637428, 2023). "Besides, the role of CP in glioma behavior was also presented." (PMID 37637428, 2023). "Additionally, immune checkpoints and CP expression in gliomas showed a favorable correlation." (PMID 37637428, 2023). "Single-cell RNA-seq analysis of HRGs, including LOX, CP, and IGFBP2, was conducted across three distinct glioma datasets." (PMID 38339384, 2024). "The free copaiba CP and EXT, and both liposomes (conventional and PEGylation) with CP or with EXT, were tested in line murine glioma (C6) after 72 h of exposure to evaluate the cell viability." (PMID 36839993, 2023). "There is a lower expression of CP in low-grade, IDH-mutant, and chemotherapeutic sensitivity glioma." (PMID 37637428, 2023). "The link between the CP expression and World Health Organization (WHO) grade in glioma was assessed using the TCGA, CGGA, Gravendeel, and Rembrandt glioma databases." (PMID 37637428, 2023). "Although the role of CP in glioma is not clearly, CP is regarded as an attractive potential target for cancer treatment, and CP-inhibiting drugs are being investigated currently." (PMID 37637428, 2023). "By analyzing the response of cell murine glioma exposure to CP in conventional liposomes, no statistical difference in the responses between doses was observed, except for 30 μg/mL, and for median EC50 23.13 μg/mL ratio (22.53–24.93 μg/mL)." (PMID 36839993, 2023). "CP expression and carcinogenesis are known to be closely related, although there is currently no information on how CP contributes to the pathophysiology, clinical relevance of glioma or its prognosis." (PMID 37637428, 2023). "CP expression was upregulated significantly in glioma tissues in comparison to non-tumor tissues and increased with glioma grades." (PMID 37637428, 2023). "In the present study, the relevant pathways and biological functions of CP were investigated using KEGG and GO pathway enrichment analyses to further investigate the mechanism of action of CP in glioma progression and its relationship with immune microenvironment." (PMID 37637428, 2023). "In marked contrast (and unexpectedly), when using membranes prepared from all cancer cell lines examined (C6-glioma, PC-12, HeLa, PC-3, and DU-145), neither the non-selective CBR ligand CP-55,940 nor WIN-55,212-2 produced significant displacement of [3H]CP-55,940." (PMID 35328467, 2022).
Menkes disease (14 papers, 2008 to 2025). A usually severe multisystemic disorder of copper metabolism, characterized by progressive neurodegeneration and marked connective tissue anomalies as well as typical sparse abnormal steely hair. "Low CP and/or the pancytopenia have been recognized in patients with copper deficiency and in patients with Menkes disease, an X-linked disorder of copper transport due to mutations in ATP7A." (PMID 37296680, 2023). "In humans, CP mutations cause a rare disorder named Menkes disease, also known as kinky hair disease, characterized by trichothiodystrophy and steely hair." (PMID 32615938, 2020). "In the case of ATP7A related disorders (Menkes disease or occipital horn syndrome), the uptake of intestinal copper is deficient, leading to low serum copper, low ceruloplasmin but also low copper in liver tissue." (PMID 29321044, 2018). "The other conditions with low ceruloplasmin levels are zinc excess, protein-losing enteropathy, Menke’s disease, and post-gastric bypass or bariatric surgeries." (PMID 40151732, 2025). "Classical Menkes disease is characterized by low serum copper and ceruloplasmin concentrations, leading to multiple abnormalities in the whole-body, especially in connective tissue and central nervous system." (PMID 38926644, 2024). "The importance of ceruloplasmin in iron metabolism is demonstrated by the fact that decreases in active ceruloplasmin, as seen in Wilson or Menkes disease, is characterized by a strong accumulation of iron in liver, spleen, and brain." (PMID 28118841, 2017). "The investigation finding of low serum copper, ceruloplasmin, hair structures are characteristics of Menkes disease." (PMID 18801184, 2008). "However, importantly, serum ceruloplasmin can also be decreased in diseases such as Menkes disease, nephrotic syndrome, protein-losing enteropathy, and various chronic liver diseases." (PMID 38622515, 2024).
Cirrhosis (13 papers, 2013 to 2025). A chronic disorder of the liver in which liver tissue becomes scarred and is partially replaced by regenerative nodules and fibrotic tissue resulting in loss of liver function. "Multiple studies have reported an association between CP mutations and increased liver inflammation, cirrhosis and hepatocellular carcinoma (HCC)." (PMID 25788186, 2015). "Associations were shown between the mean CP value and gender, inflammation stage, fibrosis stage, and cirrhosis status for all subjects in the training group (all P-values<0.05)." (PMID 24282481, 2013). "Multivariate analysis showed that CP levels were all significantly associated with cirrhosis in males." (PMID 24282481, 2013). "As a final limitation of our study, we did not analyze potential confounders such as some complications of cirrhosis, drug therapies, nutritional status, or ceruloplasmin and metallothionein levels." (PMID 40724821, 2025). "We then evaluated the fucosylation level of the glycoprotein ceruloplasmin among 62 patient samples (35 cirrhosis, 27 early-stage NASH HCC) by LC-Stepped HCD-PRM-MS/MS to quantitatively analyze 18 targeted glycopeptides." (PMID 35372033, 2022). "The highest difference in the peak areas of the fucosylated glycopeptide was observed for the tetra-antennary glycoform of the ELHHLQEQNVSNAFLDK glycopeptide of ceruloplasmin which is on average 7.5 fold higher in the cirrhosis groups." (PMID 34857845, 2021). "This study aimed to investigate associations between ceruloplasmin (CP) levels, inflammation grade and fibrosis stages in patients with chronic hepatitis B (CHB) and to establish a noninvasive model to predict cirrhosis." (PMID 24282481, 2013). "Univariate logistic regression analysis showed significant associations between cirrhosis and markers, including albumin, globulin, CHE, PT, INR, PLT, AFP, and CP (all P-values<0.05)." (PMID 24282481, 2013). "Patients with cirrhosis: low or very low ceruloplasmin (<5 mg/dL); increased 24-h urinary copper excretion (>100 μg/24 h); increased non-ceruloplasmin-bound copper; increased hepatic copper levels (>250 μg/g); thrombocytopenia; increased international normalized ratio." (PMID 40197188, 2025). "Other causes for cirrhosis were effectively ruled out with negative viral hepatitis, ceruloplasmin levels, and the HFE gene." (PMID 38559525, 2024). "Furthermore, combined serum IGF-1 levels and CP scores (IGF-CP score) more accurately predict 1 year mortality than CP or model for end-stage liver disease (MELD) scores alone in patients with decompensated cirrhosis." (PMID 37554499, 2023). "Additionally, we used a combination of routinely measured clinical parameters along with serum CP to establish a noninvasive model to predict and assess fibrosis and cirrhosis." (PMID 24282481, 2013). "Notably, even those with cirrhosis had a relatively good hepatic reserve with a CP score of ≤7." (PMID 39873460, 2025). "Among the biochemical markers assessed, we showed that albumin, globulin, GGT, CHE, TBA, PT, INR, CP and PLT were predictors of cirrhosis." (PMID 24282481, 2013). "Subjects with cirrhosis had lower CP values compared to subjects without cirrhosis (P<0.001)." (PMID 24282481, 2013). "This is likely the case of the ELHHLQEQNVSNAFLDK glycopeptide of ceruloplasmin where the tetra-antennary non-fucosylated glycoform has higher intensity in the cirrhosis groups while the bi-antennary glycoform is slightly lower in cirrhosis than in the healthy controls." (PMID 34857845, 2021). "Another study of patients with decompensated cirrhosis (without HCC) revealed that serum IGF-1 levels (median: 70.1, 40.5, and 32.4 ng/mL for CP class A, B, and C, respectively) and IGF-CP scores were associated with 1 year mortality." (PMID 37554499, 2023). "We used a comparative analysis of patients with and without cirrhosis and identified a combination of 4 variables (AFP, PT, PLT and CP) that we used in our predictive model, APPCI." (PMID 24282481, 2013).